SPIN3 (spindlin family member 3)
Description:
Exhibits H3K4me3-binding activity.
Synonyms: SPIN-3; TDRD27; bA445O16.1
Tractability: Small molecule: a high-quality ligand is known. PROTAC: ubiquitination databases record sites on it; a small molecule that binds it is known.
Target class: Reader; Epigenetic regulator
Chemical probes: VinSpinIn (high quality)
Gene: Protein-coding gene on chromosome X (56,818,298 to 56,995,827, reverse strand). Ensembl gene ENSG00000204271.
Subcellular location (Human Protein Atlas): Nucleoplasm
Gene Ontology:
Molecular function: histone H3K4me3 reader activity; protein binding
Biological process: regulation of DNA-templated transcription; chromatin organization; gamete generation
Cellular component: nucleoplasm
Homologues: Orthologues: macaque SPIN3 (98% identical), tropical clawed frog spin1 (84% identical), zebrafish spina (78% identical), pig SPIN3 (56% identical), zebrafish spinb (54% identical). Paralogues in human: SPIN1 (84% identical), SPIN2B (74% identical), SPIN2A (74% identical), SPIN4 (67% identical).
Diseases named in the same sentence as SPIN3 in open-access papers:
SPIN3 is named in the same sentence as 6 diseases in open-access papers, as found by Europe PMC text mining. Sharing a sentence is not in itself a finding about the gene and the disease. The quoted sentences say what the papers report.
cervical carcinoma (1 paper, 2018). A carcinoma arising from either the exocervical squamous epithelium or the endocervical glandular epithelium. "In line with this, we observed similar patterns in HeLa cervical carcinoma cells overexpressing SPIN1 and SPIN3, but not in HEK293T cells, which do not originate from a tumor." (PMID 30197756, 2018).
seminoma (1 paper, 2018). A radiosensitive malignant germ cell tumor found in the testis (especially undescended), and extragonadal sites (anterior mediastinum and pineal gland). "Here, we investigated the functional significance of SPIN1 and its structurally similar paralogue, SPIN3, with respect to apoptosis and cell cycle progression in the human seminoma cell line, TCam-2." (PMID 30197756, 2018). "Here, we examined the functional significance and regulation of SPIN1 and SPIN3 in the TCam-2 human seminoma cell line." (PMID 30197756, 2018). "The present study describes two proteins, SPIN1 and SPIN3, that play opposite roles in regulating apoptosis in the human seminoma (a type of TGCT) cell line, TCam-2." (PMID 30197756, 2018). "Given that TCam-2 male germ cells originate from a seminoma, we hypothesized that SPIN1 is a proto-oncogene and SPIN3 is a tumor suppressor in these cells." (PMID 30197756, 2018).
tumor (2 papers, 2018 to 2021). "Taken together, SPIN1 demonstrated proto-oncogenic properties, while SPIN3 showed tumor suppressor features." (PMID 33401540, 2021). "PUM1 itself, but not PUM2, strongly stimulated apoptosis and moderately slowed down cell cycle progression, suggesting that PUM1, similarly to SPIN3, plays the role of a tumor suppressor in TCam-2 cells." (PMID 33401540, 2021). "We also found that PUM1 itself strongly stimulated apoptosis and moderately slowed cell cycle progression in TCam-2 cells, suggesting that PUM1, like SPIN3, is a tumor suppressor." (PMID 30197756, 2018). "In contrast with its proposed role as a tumor suppressor, SPIN3 also promoted cell cycle progression, and this requires further study." (PMID 30197756, 2018). "It appears that SPIN1 is pro-oncogenic and SPIN3 acts as a tumor suppressor in TCam-2 cells." (PMID 30197756, 2018). "This exogenous expression imbalance between pro-oncogenic SPIN1 and tumor-suppressing SPIN3 may reflect a mechanism used by TCam-2 cells to maintain tumor phenotype." (PMID 30197756, 2018). "Our results strongly suggest that SPIN1 is a proto-oncogene, while SPIN3 is a tumor suppressor." (PMID 30197756, 2018). "SPIN3 downregulation may thus be typical only for tumor-derived cells, but not for non-tumor cells, supporting our hypothesis that SPIN3 might be a tumor suppressor." (PMID 30197756, 2018).
cancer (1 paper, 2018). A tumor composed of atypical neoplastic, often pleomorphic cells that invade other tissues. "Our findings suggest that acting, at least in part, through SPIN1 and SPIN3, PUM proteins contribute to a mechanism promoting normal human male germ cell apoptotic status and thus preventing cancer." (PMID 30197756, 2018). "Similarly, SPIN1 upregulated and SPIN3 downregulated CYCD1, which is a downstream target of the PI3K/AKT pathway and contributes to apoptosis resistance in cancer cell lines." (PMID 30197756, 2018). "Because SPIN1 mediates PI3K/AKT signaling to promote apoptosis resistance in cancer cell lines, we performed real-time qRT-PCR to test whether SPIN1 or SPIN3 affected the downstream targets of that pathway." (PMID 30197756, 2018). "In conclusion, our results suggest that at least in part through SPIN1 and SPIN3, PUM proteins may work as part of a mechanism promoting normal germ cell apoptotic status and thus preventing cancer." (PMID 30197756, 2018).
infection (1 paper, 2020). The state of being infected such as from the introduction of a foreign agent such as serum, vaccine, antigenic substance or organism. "We also found that sphk-1 (p = 0.0086), spin-2 (p < 0.0001), and spin-3 (p < 0.0001) mutant worms were significantly more susceptible to infection by E. faecalis strain MMH594, whereas spin-4 (p = 0.0222) mutant worms were modestly more resistance than N2." (PMID 33105563, 2020).
SPIN3 also shares sentences with these, for which no sentence is quoted: glioma (1 paper).